SPINT1 (serine peptidase inhibitor, Kunitz type 1)
Diseases named in the same sentence as SPINT1 in open-access papers (continued):
Sharing a sentence is not in itself a finding about the gene and the disease.
placental insufficiency (continued). "Notably, low levels of SPINT1 have recently been shown to be a marker of placental insufficiency and fetal growth restriction." (PMID 37224249, 2023). "Our work identifies low circulating SPINT1 as a marker of placental insufficiency." (PMID 32415092, 2020). "Given circulating SPINT1 may reflect true placental insufficiency, it has the potential to be applied in a variety of other clinical situations to reduce the stillbirth risk, such as monitoring fetuses with co-existing obstetric complications, or those that are post term." (PMID 32415092, 2020). "In the search for circulating biomarkers of placental insufficiency, SPINT1, a serine protease inhibitor, also called HGF activator inhibitor 1 (HAI-1), has been identified as a promising candidate." (PMID 34299087, 2021). "Thus, our data suggests low circulating SPINT1 levels may reflect genuine placental insufficiency, not just low birthweight." (PMID 32415092, 2020). "Unlike SPINT1, circulating SPINT2 is not consistently dysregulated in diseases of placental insufficiency—in preeclampsia or foetal growth restriction." (PMID 34299087, 2021).
squamous cell carcinoma (4 papers, 2017 to 2020). A carcinoma arising from squamous epithelial cells. "Although SPINT1 is a serine protease inhibitor with several targets, including ST14 and HGFA, deregulation of the SPINT1/ST14 axis leads to spontaneous squamous cell carcinoma in mice and keratinocyte hyperproliferation in zebrafish preceded by skin inflammation in both models." (PMID 31519199, 2019).
colitis (3 papers, 2008 to 2017). Inflammation of the colon. "Further, during the course of acetic acid-induced experimental colitis in an in vivo mouse model, Spint1 but not Spint2 was upregulated in the recovery phase, a process that requires cellular regeneration." (PMID 18506145, 2008).
skin cutaneous melanoma (3 papers, 2019 to 2021). "We localized the mutation to a single locus which contains a strong candidate gene, SPINT1, a tumor suppressor implicated in human skin cutaneous melanoma (SKCM) and over-proliferation of epithelial cells in mice and zebrafish." (PMID 34166378, 2021). "This locus contains a strong candidate gene, SPINT1, a tumor suppressor implicated in human skin cutaneous melanoma." (PMID 34166378, 2021). "Furthermore, SPINT1 deficiency was used to establish a disease model for Skin Cutaneous Melanoma (SKCM) in zebrafish." (PMID 34166378, 2021). "Reduced expression of SPINT1 has been associated with a negative prognosis of human Skin Cutaneous Melanoma (SKCM) and pancreatic ductal adenocarcinoma." (PMID 34166378, 2021). "Of note, alterations in the SPINT1 gene are highly prevalent in skin cutaneous melanoma (SKCM) patients and may promote metastatic invasion." (PMID 32602849, 2020).
fetal growth restriction (2 papers, 2020 to 2023). A fetus that does not grow beyond the 10th percentile of conventionally accepted weight for gestational age. "We validate the association between low circulating SPINT1 concentrations in a cohort from the United Kingdom and in women with preterm fetal growth restriction." (PMID 32415092, 2020). "Placental Spint1 mRNA and SPINT1 protein expression were significantly reduced among cases where maternal hypoxia-induced fetal growth restriction." (PMID 32415092, 2020).
melanoma (2 papers, 2019 to 2020). A malignant, usually aggressive tumor composed of atypical, neoplastic melanocytes. "Furthermore, more aggressive melanomas were observed in a SPINT1-deficient background in zebrafish, suggesting that SPINT1 deficiency accelerates melanoma formation via altered immune cell recruitment and activity." (PMID 32455885, 2020). "They noted that a subset of melanoma patients had high levels of SPINT1 mRNA, and this upregulation correlated with poor prognosis and greater tumor-associated macrophage infiltration." (PMID 32455885, 2020). "Recently, Gόmez-Abenza and colleagues discovered that serine peptidase inhibitor, Kunitz type 1 (SPINT1) regulated melanoma aggression and crosstalk in the tumor microenvironment." (PMID 32455885, 2020). "In this study, we have developed a preclinical zebrafish model to study the role of SPINT1-driven skin chronic inflammation in melanoma." (PMID 31519199, 2019).
preeclampsia (2 papers, 2021 to 2022). Preeclampsia is a hypertensive disorder of pregnancy that is characterized by new-onset hypertension with proteinuria presenting after 20 weeks of gestation, and depending on mild or severe forms may initially present with severe headache, visual disturbances, and hyperreflexia. "We previously reported significantly reduced SPINT1 concentrations in the circulation of normotensive pregnancies complicated by preterm FGR, however this is the first time SPINT1 has been examined in association with preterm preeclampsia." (PMID 35207174, 2022). "This study explored the potential that SPINT1 might be associated with preterm FGR in the presence of coexisting preeclampsia (around 30 weeks’ gestation)." (PMID 35207174, 2022). "It was therefore hypothesised that SPINT1 perturbations associated with FGR might also be observed in those with a primary diagnosis of preeclampsia." (PMID 35207174, 2022). "Our finding that SPINT1 is differentially expressed in pregnancies complicated by both preeclampsia and FGR provides further understanding of the pathogenesis of these disorders." (PMID 35207174, 2022). "We hypothesised that circulating SPINT1 would be decreased in co-existing preterm preeclampsia and FGR." (PMID 35207174, 2022). "Although our prior work demonstrates reductions in SPINT1 are associated with poor fetal growth, no studies have found its expression to be deranged in preeclampsia." (PMID 35207174, 2022). "As expected, PlGF was particularly reduced in the pregnancies complicated by both preeclampsia and FGR, while a ratio of sFlt-1/SPINT1 was significantly elevated in a similar manner to that observed for sFlt-1/PlGF." (PMID 35207174, 2022). "Indeed, we found in two separate cohorts that SPINT1 was markedly reduced in the plasma of patients with preeclampsia delivering SGA infants and preeclampsia, relative to those women with preeclampsia carrying appropriately grown infants." (PMID 35207174, 2022). "This new study provides the first insights into SPINT1 possibly being deranged in preterm growth restriction, irrespective of co-existing preeclampsia." (PMID 35207174, 2022). "In this study, we therefore measured circulating SPINT1 protein levels in women with pregnancies complicated by preterm preeclampsia, to assess whether SPINT1 was differentially expressed among those with and without an SGA infant at birth." (PMID 35207174, 2022).
breast tumor (1 paper, 2023). "RNA-sequencing of wild-type versus HIF-2α-deficient TAMs in murine breast tumors demonstrated 3 more genes Spint1, IL-10, and Depdc7 were downregulated by HIF-2α knockout and had an identified HIF-2α (not HIF-1α) binding site using previously published ChIP-seq data sets." (PMID 37124241, 2023). "Spint1 is a tumor suppressor and recombinant Spint1 inhibited E0771 breast tumor cell proliferation, in vitro." (PMID 37124241, 2023). "Further investigation of Spint1, demonstrated HIF-2α-deficient BMDMs produce less Spint1 tumor suppressor than controls regardless of oxygen concentration resulting in faster orthotopic breast tumor growth, suggesting a paracrine role for HIF-2α in tumor suppression." (PMID 37124241, 2023).
epithelial ovarian tumor (1 paper, 2019). "SPINT1 (matriptase, HAI-2) is a type II transmembrane serine protease expressed on epithelial ovarian tumor cells." (PMID 31240259, 2019).
Fulminant hepatitis (1 paper, 2018). Acute hepatitis complicated by acute liver failure with hepatic encephalopathy occurring less than 8 weeks after the onset of jaundice. "In addition, enhanced immunoreactivity of HAI-1/SPINT1 occurs in the gastrointestinal epithelium at the edge of ulcers, periportal hepatocytes of advanced primary biliary cholangitis (PBC), fulminant hepatitis and also in the interlobular biliary epithelium of PBC patients." (PMID 30388869, 2018).
insulinomas (1 paper, 2015). "A lower RNA expression of the inhibitor of matriptase SPINT1 was detected in the insulinoma metastases, potentially contributing to increased activity of matriptase to participate in HGF activation." (PMID 26435753, 2015). "The final effect of the increased expression of HGF, its activator (matriptase) and its specific receptor (MET) together with a decreased expression of one potent inhibitor of matriptase (SPINT1) is probably a contribution to tumoral progression and metastatization in insulinomas." (PMID 26435753, 2015).
nevus (1 paper, 2019). Nevus (or naevus, plural nevi or naevi, from nævus, Latin for "birthmark") is the medical term for sharply circumscribed[1] and chronic lesions of the skin or mucosa. "Notably, these genetic alterations of SPINT1 significantly correlated with poor SKCM patient prognosis and SPINT1 expression was significantly inhibited in human SKCM comparing with nevus and normal skin." (PMID 31519199, 2019).
non-small cell lung carcinoma (1 paper, 2024). A group of at least three distinct histological types of lung cancer, including non-small cell squamous cell carcinoma, adenocarcinoma, and large cell carcinoma. "SPINT1 is a hepatocyte growth factor activator inhibitor-1 (HAI-1) that promotes M1 macrophages and inhibits M2 macrophages, resulting in improved outcomes for patients with non-small cell lung carcinoma." (PMID 39684750, 2024).
skin squamous cell carcinoma (1 paper, 2021). A carcinoma arising from the squamous cells of the epidermis. "Increased expression of SPINT1 in the skin abrogated matriptase-induced spontaneous skin squamous cell carcinoma." (PMID 34166378, 2021).
varicocele (1 paper, 2024). A condition characterized by the dilated tortuous veins of the spermatic cord with a marked left-sided predominance. "Whole-exome sequencing in a cohort of patients with varicoceles has identified multiple genetic variants associated with varicoceles (e.g., AAMP, SPINT1, or MK167)." (PMID 38392299, 2024).
cancer (49 papers, 2006 to 2026). A tumor composed of atypical neoplastic, often pleomorphic cells that invade other tissues. "Accordingly, smoking status was among the top three variables explaining plasma variation in the most differentially expressed proteins in patients with cancer, Kunitz-type protease inhibitor 1 (SPINT1) (3.0%)." (PMID 41068475, 2025). "According to previous findings, SPINT1 expression strongly affects E-cadherin expression in association with the expression of SIP1, an E-cadherin transcriptional repressor, in specific carcinoma cell lines." (PMID 40507942, 2025). "CellMiner, a query tool for the NCI-60 cancer cell lines, was used to analyze the relationship between SPINT1 expression and cetuximab sensitivity in a variety of cancer cell lines." (PMID 38212428, 2024). "We used bioinformatics analysis to identify MET Transcriptional Regulator (MACC1) and Serine Peptidase Inhibitor Kunitz Type 1 (SPINT1) as candidate TFs with the respective downstream regulatory proteins for patient prognosis in pan‐cancer." (PMID 33751856, 2021). "Downregulation of proteins involved in the mitochondrial respiratory chain like NFU1, ACO2, PDHA1, and proteins like DECR1, CNDP2, and SPINT1, which have a tumor suppressive role in different cancers were noted." (PMID 34885041, 2021). "Here, we performed a bioinformatics and molecular analyses of clinical samples for the identification of a MACC1/SPINT1 panel as a pan‐cancer prognostic tool." (PMID 33751856, 2021). "It was without exception that the AUCs for OS and DFS for the signature in the eight cancers were elevated, compared with those for MACC1 or SPINT1 separately, indicating that the MACC1/SPINT1 signature was an effectively prognostic model in these cancers." (PMID 33751856, 2021). "Kaplan‐Meier plots and receiver operating characteristics analysis revealed that the two‐gene signature combining MACC1 with SPINT1 was effective in predicting survival in all eight cancer cohorts tested." (PMID 33751856, 2021). "As previous studies reported, the biological functions of MACC1 and SPINT1 can be observed in variety of cancers." (PMID 33751856, 2021). "Knockdown of SPINT1 expression by siRNA in cancer cell lines led to increased invasion or metastasis." (PMID 34166378, 2021). "The functional linkage between ST14 and SPINT1 has important implications for the development of cancer." (PMID 31519199, 2019). "Because the increased ratio of ST14/Prss14 to its inhibitor SPINT1 was observed in some carcinomas, we examined the ratio of ST14/Prss14 to SPINT1 and SPINT2." (PMID 27167193, 2016). "We focused on MACC1 and SPINT1, which were identified as important molecules for further investigation of their transcriptional regulatory relationship, biological functions in GC cells, and pan‐cancer prognostic value." (PMID 33751856, 2021). "Indeed, loss of cell surface HAI-1 frequently occurs in cancer cells in vivo due to decreased SPINT1 mRNA levels and/or enhanced shedding of the HAI-1 extracellular domain." (PMID 29202869, 2017). "Furthermore, we have established the predictive signature model combining MACC1 with SPINT1 for prognosis prediction in patients with GC and other seven cancer types, which will lay a foundation for the development of new biomarkers and targeted therapies in multiple cancer types." (PMID 33751856, 2021). "Besides, MACC1/SPINT1 panel was established to effectively predict survival in eight cancers." (PMID 33751856, 2021). "In Pt2, five integrations with total frequencies of more than 1% were observed near or in cancer-related genes (DPP4, TNFAIP3/PERP, MLLT10, EPS8, and SPINT1)." (PMID 34786435, 2021). "Previously, we reported that silencing of SPINT1 by short hairpin RNA enhanced the invasive capacity of cancer cells, including OSCC cells, indicating that HAI-1 is a suppressor of cancer cell invasion." (PMID 29545930, 2018).
cancer (continued). "HSPB1 is frequently upregulated in BC, wherein it promotes cancer cell growth and metastasis by inducing the SUMOylation of HSPB8 and increasing its expression, and SPINT1 was highly expressed in the HER2-positive type, with a relatively high rate in node-positive patients." (PMID 36428562, 2022). "The combined analysis of RNA-seq and ChIP-seq for H2A.Z showed downstream gene regulation to mainly occur via the transcriptional misregulation in the cancer pathway, its target genes mainly including TCF3 CDK14, JUP, SPINT1, CDKN1A, and IGF1, each of which corresponded to different cell phenotypes." (PMID 34120148, 2021). "In addition, we found that acetylation of H2A.Z in HCC could change the chromatin status and promote the transcription of downstream genes, including TCF3, CDK14, JUP, SPINT1, CDKN1A, and IGF1, which are important regulatory molecules in the cancer misregulation pathway." (PMID 34120148, 2021). "The ratio of ST14/Prss14 to SPINT1, ratio(I), and that of ST14/Prss14 to SPINT2, ratio(II), showed no big difference among the cancer stages." (PMID 27167193, 2016).
tumor (40 papers, 2006 to 2025). "These animals maintain iridophores to adulthood and are prone to the development of iridophoroma, a tumor of iridophores, due to a mutation in SPINT1, which is a tumor suppressor." (PMID 38976731, 2024). "Second, loss of SPINT1 function in fish and mice leads to tumor formation in epithelial cells." (PMID 34166378, 2021). "In brief, our study suggested that MACC1/SPINT1 panel can be a reliable prognostic indicator, which provides an advance in tumor prognosis research." (PMID 33751856, 2021). "The tumor suppressor function of SPINT1 establishes a potential link between iridophoroma and regulation of white coloration in reptiles." (PMID 34166378, 2021). "We report here a high prevalence of SPINT1 genetic alterations in SKCM patients and their association with altered tumor immune microenvironment and poor patient survival." (PMID 31519199, 2019). "Collectively, these results suggest that both high and low levels of SPINT1 result in an unbalanced crosstalk between tumor cells and their microenvironment promoting higher aggressiveness." (PMID 31519199, 2019). "Moreover, the promoter region of SPINT1, represented by the specific probe cg22491225, is hypermethylated in tumor samples compared to normal tissue." (PMID 38212428, 2024). "All three negative regulators, the endogenous protease inhibitors, demonstrated a trend for reduced mRNA expression in tumor tissues compared to normal, with SPINT1 and SERPINA5 having a reduction in mRNA expression that reached statistically significant levels." (PMID 38212428, 2024). "Intestine-specific deletion of SPINT1 leads to increased tumor growth of intestine epithelium." (PMID 34166378, 2021). "Therefore, both high and low levels of SPINT1 result in an unbalanced crosstalk between tumor cells and their microenvironment promoting higher SKCM aggressiveness." (PMID 31519199, 2019). "However, a negative correlation of SPINT1 and EMT marker levels was observed, suggesting that SPINT1 levels critically regulate tumor and immune cell crosstalk." (PMID 31519199, 2019). "While there is a slightly higher tumor mutational burden in EPAS1-altered tumors (9.9 vs. 4.9 mut/Mb), they are enriched in and associated with genes promoting immune evasion, including ARID5B, SPINT1, AAK1, CLIC3, SORT1, SASH1, and FGFR3, respectively (q < 0.001)." (PMID 36421334, 2022). "Moreover, the highest HR was detected in the correlation between SPINT1 expression and DMFS in HER2+ patients (HR = 7.74, P = 0.0011), suggesting that SPINT1 influenced patient clinical outcomes, possibly by affecting tumor metastasis, particularly in the HER2+ subgroup." (PMID 34381422, 2021). "Through the use of a zebrafish line deficient of serine peptidase inhibitor kunitz type 1 (SPINT1), they showed that SPINT1 levels positively correlated with rates of macrophage infiltration into the TME, indicating its regulation of the crosstalk between tumor cells and the immune system." (PMID 34095125, 2021). "However, the number of tumor-associated neutrophils (TAN) was independent of SPINT1 levels in both primary and metastatic SKCM." (PMID 31519199, 2019). "We have reported that in ApcMin/+ mice, targeted disruption of the Spint1 gene that encodes HAI-1 resulted in significantly increased amounts of tumor formation, whereas activation of HGF/SF in the intestine was enhanced in HAI-1-deficient tumors and non-tumor mucosa." (PMID 25268161, 2014). "Of note, seventeen of thirty-nine proteins are reported as urine biomarkers in different diseases, of which eight proteins (PEBP1, EPS8L2, SERPINA1, FGA, SPINT1, CD55, SPARC, and GINM1) are related to neoplastic disease in urine specimens." (PMID 36918772, 2023). "Here, we used molecular approach to demonstrate that SPINT1 serves as a downstream signaling protein of MACC1, participating in tumor genesis and progression through HGF/c‐Met signaling pathway." (PMID 33751856, 2021).